RN7SL681P (RNA, 7SL, cytoplasmic 681, pseudogene)
Gene: Miscellaneous RNA gene on chromosome 4 (87,386,883 to 87,387,174, reverse strand). Ensembl gene ENSG00000240966.
Homologues: Orthologues: chimpanzee Metazoa_SRP (93% identical), macaque Metazoa_SRP (90% identical), dog Metazoa_SRP (69% identical). Paralogues in human: RN7SL1 (78% identical), RN7SL2 (77% identical), RN7SL3 (76% identical), RN7SL709P (76% identical), RN7SL220P (76% identical), RN7SL333P (76% identical), RN7SL530P (75% identical), RN7SL45P (75% identical), RN7SL478P (75% identical), RN7SL650P (75% identical), RN7SL769P (75% identical), RN7SL788P (75% identical), and 703 more.